MYB (MYB proto-oncogene, transcription factor)
Diseases named in the same sentence as MYB in open-access papers (continued):
Sharing a sentence is not in itself a finding about the gene and the disease.
leukemia (continued). "Our work here shows that MYB can confer resistance to sorafenib via upregulating FTH1 and inhibiting sorafenib-induced ferroptosis in human leukemia." (PMID 40725394, 2025). "MYB inhibits sorafenib-induced ferroptosis by upregulating FTH1, thereby endowing human leukemia cells with resistance to sorafenib." (PMID 41584591, 2025). "The developed peptidomimetic downregulated the MYB-bound BCL2 enhancer, leading to the downregulation of BCL2 expression and apoptosis of leukaemia cells." (PMID 40243822, 2025). ",112,114, 115, 116, 117,168 IGF2BP1 promotes the self-renewal and initiation of leukemia stem cells as well as the sensitivity of leukemia cells to the alkylating agents by regulating the expression of ALDH1A1, HOXB4, and MYB." (PMID 40584294, 2025). "The fusion partner evidently plays a role in the leukemogenicity of the MYB fusion, since MYB::PLEKHO1 can induce leukemia independently while MYB-TR requires KO of Cdkn2a." (PMID 39499902, 2024). "MYB and lymphoid enhancer-binding factor-1 (LEF-1) cooperated in the prevention of apoptosis in the leukemia cells, and GSK3β inhibition was able to circumvent this anti-apoptotic pathway." (PMID 38835346, 2024). "To investigate how BPDCN MYB fusions induce leukemic transformation of Hoxb8-FL progenitor cells, we performed CUT&RUN in MYB::PLEKHO1 leukemia cells using an anti-V5 antibody to detect chromatin occupancy of the exogenously expressed fusion protein." (PMID 39499902, 2024). "Hoxb8-FL cell–derived leukemia was almost fully penetrant in Cdkn2a-WT MYB::PLEKHO1, Cdkn2a-KO MYB-TR, and Cdkn2a-KO MYB::PLEKHO1 recipient mice but was rarely observed in other genotypes and only with significantly longer latency." (PMID 39499902, 2024). "MYB physically binds to the promoter of the miR-155 host gene (MIR155HG) and stimulates its transcription, which leads to leukemia." (PMID 39758420, 2024). "In keeping with this, CIMP leukemias also exhibited increased methylation at NOTCH1, MYB, and TAL1 binding sites than ETP-ALL, and hypomethylation of TFBS for myeloid master regulators such as CEBPA, CEBPB, and SPI1." (PMID 38972954, 2024). "Truncated forms of MYB were first discovered as viral inducers of avian leukemias and were subsequently shown to contribute to leukemic transformation in mouse hematopoietic cells, but whether and how they might be involved in human leukemia has remained unclear." (PMID 39499902, 2024). "Hoxb8-FL cell–derived MYB-TR and MYB::PLEKHO1-driven leukemias were positioned between myeloid progenitors, monocytes, and DCs, consistent with their surface protein marker expression." (PMID 39499902, 2024). "In leukemia, IGF2BP1 increases the stemness of leukemia cells by positively regulating the hematopoietic stem cell regulators HOXB4 and MYB, as well as the stem cell marker ALDH1A1." (PMID 38328550, 2024). "In leukemia, METTL14, which is negatively regulated by SPI1, exerts its oncogenic effects by regulating m6A modification of its mRNA targets (e.g., MYB and MYC)." (PMID 37932821, 2023). "METTL14 has also been reported in leukemia; METTL14 exerts oncogenic effects by regulating its mRNAs (MYB and MYC) through m6A modifications." (PMID 35487915, 2022). "We previously showed that overexpression of MIR29B resulted in a significant decrease in expression of MYB, a known HBG repressor protein, in KU812 leukemia cells." (PMID 36507536, 2022). "Further investigation confirmed MYB silencing markedly decreased ALKBH5 mRNA and protein amounts in leukemia cells." (PMID 35063010, 2022). "We previously found that MSI2 maintains MLL-leukemia self-renewal programs by retaining the translation of HOXA9, c-MYC, MYB, and IKZF218,31." (PMID 36167829, 2022). "Previous results found that Reptin is required for the oncogenic potential of leukemia, and silencing Reptin resulted in AML cell apoptosis in engrafted mice by increased transcriptional activation c-MYB." (PMID 35754815, 2022).
leukemia (continued). "MYB expression is essential for the initiation and maintenance of MLL-fusion induced AML, and indeed these leukaemias are particularly sensitive to MYB inhibition when compared to normal haematopoietic cells and leukaemias induced by several other oncogenes." (PMID 31882723, 2019). "Next, MYB mRNA levels were measured in both MOLM13 and murine MLL-AF9 leukaemia cells following treatment with each CDK9 inhibitor." (PMID 31882723, 2019). "In SPI1-METTL14-MYB/MYC axis, METTL14, is downregulated by SPI1, exerts an oncogenic role in enhancing leukemia stem/initiating cells self-renewal and repressing myeloid differentiation by regulating MYB and MYC via m6A modification." (PMID 30062093, 2018). "Here, the authors develop a peptidomimetic (MYBMIM) that prevents the interaction of the trans-activation domain of MYB with the KIX domain of CBP/P300 and inhibits leukaemia growth." (PMID 29317678, 2018). "We found that MYBMIM downregulated the MYB-bound BCL2 enhancer, leading to downregulation of BCL2 expression and apoptosis of leukemia cells." (PMID 29317678, 2018). "For example, CRISPR/Cas9‐mediated deletion (191 bp) of −7.5 kb upstream regions of TAL1, which is bound by the transcription factor MYB, reduced the expression of TAL1 by ~85% in human Jurkat leukemia cells." (PMID 28255028, 2017). "MYB has been reported to directly activate the expression of CCNE1 (in normal and transformed colonic epithelium and CCNB1 (in leukaemia and breast cancer cells;." (PMID 26812885, 2016). "In myeloid leukemias, MYB has been shown to be a critical target of known oncogenes, including HOXA9 and MLL fusions, and has been identified as a part of a leukemia stem cell maintenance signature." (PMID 27863435, 2016). "Here, we showed that MYB can upregulate FTH1, inhibit ferroptosis in human leukemia cells." (PMID 40725394, 2025). "In leukemia stem cells (LSCs), KDM4C enhances ALKBH5 level by elevating chromatin accessibility at the ALKBH5 locus, diminishing H3K9me3 levels, and facilitating the binding of MYB and Pol II." (PMID 40186131, 2025). "Furthermore, it has been reported that MLL and CBP, together with CREB or MYB, form a ternary complex in vitro, and inhibitors targeting the MYB:CBP/P300 complex are very efficient at suppressing the survival of leukaemia cells harbouring MLLr." (PMID 38671157, 2024). "Directly inhibiting the transactivation function of MYB has garnered increased attention as a potential therapeutic strategy, given recent insights into its role in leukemia and certain non-hematopoietic malignancies." (PMID 38542205, 2024). "Celastrol, in addition to inhibiting MYB’s transcriptional activity, reduced the proliferative capacity of AML cells, induced their differentiation and apoptosis and delayed the development of leukemia in an in vivo mouse model of AML." (PMID 38542205, 2024). "For example, in leukemia, METTL14 was shown to promote stemness by inducing MYC and MYB expression." (PMID 39563370, 2024). "To investigate why MYB::PLEKHO1 but not MYB-TR initiated leukemia in Cdkn2a-WT Hoxb8-FL cells, we developed a system to culture MYB-expressing Hoxb8-FL cells in vitro without requiring Hoxb8 activation." (PMID 39499902, 2024). "However, MYB plays a pivotal role for the proliferation and survival of the AML cells transformed by other leukemia oncogenes." (PMID 38542205, 2024). "Cdkn2a-WT MYB::PLEKHO1 leukemias showed intact expression of p16INK4A and p19ARF, while Cdkn2a-KO leukemias did not, confirming that MYB::PLEKHO1 is indeed able to induce leukemia independently of Cdkn2a loss." (PMID 39499902, 2024). "MYBMIM led to MYB-p300 dissociation, suppression of MYB activity followed by downregulation of MYC and BCL2, apoptosis induction in AML cells, and prolonged survival in patient-derived MLL-rearranged leukemia mouse model." (PMID 38835346, 2024). "MYB fusions, but not MYB-WT, are able to induce myeloid/dendritic leukemia in vivo when expressed in hematopoietic progenitor cells." (PMID 39499902, 2024).
leukemia (continued). "Meanwhile, results of T-cell dysfunction value in core dataset revealed a strong positive relationship between MYB expression and T-cell dysfunction value in endometrial cancer and a strong negative relationship in leukemia." (PMID 36994664, 2023). "In the mouse AML model, shRNA-mediated MYB down-regulation resulted in the remission of leukemia without inhibition of normal myelopoiesis." (PMID 37297004, 2023). "The finding of a strong inverse correlation between MYB and MAFB in MLL-driven leukaemia suggests that MAFB could serve as a new useful prognostic biomarker or predictive toward future MYB-targeted therapeutic strategies." (PMID 37996430, 2023). "To better understand the process of how MYB reduction could lead to such a different response in different leukaemia settings, we explored the transcriptomes of FUJIOKA, MOLM14 and KASUMI1 cells 24 h after MYB silencing." (PMID 37996430, 2023). "Importantly, reduced c-MYB levels are still compatible with normal hematopoiesis, therefore inhibition of c-MYB appears to have a therapeutic opportunity for MLL-rearranged leukemia." (PMID 34594227, 2021). "Among these were RUNX1, MYB, and TAL1, 3 out of 8 DE genes (Fisher Exact test, odds ratio = 93, p = 2 × 10−5) that have previously been identified as part of a core transcriptional circuitry important to our leukemia model system." (PMID 33526072, 2021). "Furthermore, METTL14 is highly expressed in acute myelocytic leukaemia (AML) and can promote the occurrence of AML by inhibiting the degradation of MYB and MYC mRNA, promoting its translation and maintaining the self-renewal of leukaemia stem cells." (PMID 34900689, 2021). "Finally, in a study of leukaemia patients, a small DNA insertion resulting in a TFBS for MYB created an enhancer near TAL1, which led to activation of this oncogene and the onset of leukaemia." (PMID 31937202, 2020). "Since we showed above that CDK9 is essential for MLL-AF9- and MLL-ENL-driven MYB transcription in reporter assays and that it is recruited to MYB by the MLL-AF9 protein, we wished to investigate the effect of CDK9 inhibitors on MYB transcription, particularly in MLL-fusion driven leukaemia cells." (PMID 31882723, 2019). "For instance, DOT1L targets the MYB gene locus in the MV411 leukemia cells but not in the C021 or C025 melanoma cells." (PMID 29343685, 2018). "MYB-driven transcriptional coactivation with CREB-binding protein (CBP)/P300 is required for acute lymphoblastic and myeloid leukemias, including refractory MLL-rearranged leukemias." (PMID 29317678, 2018). "In this regard, full-length c-MYB is not able to induce leukemia in mice but is essential for AML maintenance in a mouse model." (PMID 29854289, 2018). "Indeed, MYB is, in turn, a target of oncogenes such as HOXA9 and MLL fusions, and contributes to a leukemia stem cell maintenance signature conferring a self-renewal capability to myeloid progenitors." (PMID 28881700, 2017). "MiR-193b-3p has been previously characterised as a regulator of transcription factors such as MYB, downstream effector of MAPK pathway and regulator of cell steaminess in different tumour types including pancreatic cancers and leukaemia." (PMID 27802451, 2016). "Given the striking upregulation of MAFB in response to MYB suppression, we reasoned that ectopic expression of MAFB could phenocopy the consequences of MYB inhibition and, as such, could represent a novel therapeutic avenue for the treatment of MLL-rearranged leukaemias." (PMID 37996430, 2023). "Thus, dissociation of the MYB:CBP/P300 complex by MYBMIM would be expected to reduce MYB-dependent occupancy and gene trans-activation at specific target genes responsible for aberrant leukemia cell growth and survival." (PMID 29317678, 2018). "In contrast to MYB-TR, MYB::PLEKHO1 did not require Cdkn2a KO to initiate leukemia in Hoxb8-FL cells." (PMID 39499902, 2024).
leukemia (continued). "GSEA of WFA-induced gene expression changes in THP1 cells revealed negative enrichment of the leukemia stem cell (LSC) self-renewal signature, consistent with the reported importance of c-MYB in maintaining the AML LSC self-renewal program and our previous data with mebendazole." (PMID 35368048, 2022). "In addition, CBP is a tumour-promoting molecule for some leukaemia types and is broadly studied in AML without MLLr, where aberrantly expressed CBP acetylates oncogenic transcription factors (such as MYB and CREB) to increase their transcriptional activity, contributing to leukemogenesis." (PMID 38671157, 2024).
breast carcinoma (96 papers, 2005 to 2025). "This study found high MYB expression in GC tissues, with poor prognosis linked to low expression, similar to breast cancer." (PMID 40672391, 2025). "MYB is overexpressed in several malignant tumors, including breast cancer, lung cancer and hepatocellular carcinoma, and is associated with tumor development." (PMID 34775376, 2021). "c-MYB is overexpressed or mutated in a variety of cancers, including breast cancer, where its expression generally correlates with that of ESR119 because ESR1 signaling positively regulates MYB expression." (PMID 30833639, 2019). "These genes, FOXA1, GATA3, and MYB, all showed greater mutation rates in ER+/luminal cancers relative to other breast cancer subtypes and, here, possessed up-regulated expression in early neoplasias relative to normal." (PMID 24887547, 2014). "MYBL1 belongs to a group of genes that encode the MYB proto-oncogene protein; MYB has been shown to be highly expressed in ER+ breast tumors and tumor cell lines and is essential for the proliferation of ER+ breast cancer cells." (PMID 24564956, 2013). "MYB is essential for mammary tumorigenesis and its upregulation is associated with estrogen receptor (ER)-positive breast cancer; NKx6-1 is a popular transcription factor involved in differentiation and development of pancreatic islet β-cells." (PMID 23056957, 2012). "MYB deregulation is also associated with colorectal cancers, carcinomas and breast cancers expressing oestrogen receptor-alpha, in which MYB has been implicated in prolactin-induced signalling pathways." (PMID 20813039, 2010). "However, the documented anti-metastatic properties of MYB in breast cancers were associated with anti-inflammatory processes such as NF-κB suppression, indicating the existence of different forms of MYB-mediated NF-κB function." (PMID 38835346, 2024). "Interestingly, MYB has also been implicated in chemoresistance in colorectal and ovarian carcinomas, as well as in endocrine resistance in luminal breast cancer cells." (PMID 38999963, 2024). "Although the contribution of MYBL1, encoding for the homolog of the oncogene MYB, to the development of breast cancer is unknown, in a previous report it was strongly induced by E2 but only marginally by phytoestrogens such as curcumin." (PMID 23305139, 2013). "The aberrant regulation of miRNA-195-5p and MYB in TNBC underscores a critical gap in the comprehension of the molecular mechanisms that drive tumorigenesis in this breast cancer subtype." (PMID 41141380, 2025). "The overexpression of MYB is widely observed in cancer cells and it’s oncogenic activity has been confirmed in leukemia, breast cancer, prostate cancer, and other cancers." (PMID 40234694, 2025). "MYB is a downstream target of ERα signaling, and its expression was high in ER+ breast cancer samples." (PMID 40190354, 2025). "Through bioinformatic analysis using the TargetScan algorithm, we identified MYB, a well-characterized oncogene in breast cancer, as a top candidate due to the presence of a highly conserved binding site for miRNA-195-5p in its 3′ untranslated region (3′UTR)." (PMID 41141380, 2025). "Given this targeting relationship, we investigated the clinical relevance of MYB expression in breast cancer progression." (PMID 41141380, 2025). "In the paclitaxel-resistant cells, the most highly upregulated genes included ones that have been associated with breast cancer metastasis, such as the platelet-derived growth factor PDGFB and the MYB oncogene." (PMID 38999963, 2024). "Selective aryl hydrocarbon receptor (AhR ) agonists (e.g., semaxanib) blocked IGF-2-mediated cell growth and reduced MYB expression in MCF-7 breast cancer cells." (PMID 38835346, 2024). "In MCF-7 breast cancer cells, knockdown of MYB led to inactivation of its anti-apoptotic target BCL2, followed by increased sensitivity to sodium butyrate-induced apoptosis." (PMID 38835346, 2024).